CRP (C-reactive protein)
Diseases named in the same sentence as CRP in open-access papers (continued):
Sharing a sentence is not in itself a finding about the gene and the disease.
cancer (continued). "CRP is a rapidly appearing marker of tissue damage and persistently elevated levels of CRP induced by inflammatory cytokines, correlate with chronic tissue irritation such as cancer-related inflammation." (PMID 38049762, 2023). "Inflammation, notably driven by factors such as C-reactive protein (CRP), is thought to participate in cancer immunoresistance by promoting tumor growth and metastasis and activating oncogenic signaling pathways." (PMID 38104105, 2023). "Within this context, these proinflammatory cytokines stimulate the liver to synthesize CRP, further contributing to muscle wasting in cancer cachexia." (PMID 37755304, 2023). "A recent review discussed the in-depth link between traditional circulating inflammatory markers, such as CRP, IL-6, and systemic inflammation in cancer patients." (PMID 36915049, 2023). "Inflammatory markers such as lymphocytes, neutrophils, or inflammation-related C-reactive protein (CRP) and albumin have prognostic significance in cancer patients and have also been used as mortality indicators." (PMID 37836440, 2023). "Significant relationships and differences of haemoglobin, CRP and albumin supports future use of these biomarkers in cancer cachexia." (PMID 37906352, 2023). "This study aims to assess the potential of CRP as an early indicator of complications, specifically AL, following esophagectomy for cancer." (PMID 37964057, 2023). "Recently, CRP and neutrophil–lymphocyte ratio (NLR) have been reported to be associated with cancer grade and poorer prognosis in not only ATC, but also DTC." (PMID 37444559, 2023). "In order to find a cost-effective prognostic biomarker for cancer patients, biochemical markers of inflammation (leucocytes and their subtypes, levels of some cytokines, CRP, albumin) have been incorporated in prognostic factors for numerous types of cancer." (PMID 37108738, 2023). "During the preoperative or postoperative period, CRP is one of the most useful parameters for evaluating the degree of inflammation in cancer patients." (PMID 36875131, 2023). "A raised level of C-reactive protein (CRP) seems to be an indicator of poor prognosis in several cancers." (PMID 36900365, 2023). "GPS, the ratio between CRP and albumin, has been extensively validated as a biomarker of poor prognosis in cancer." (PMID 37213604, 2023). "In patients diagnosed with cancer within 3 months, CRP correlated with IL‐6 (r = 0.75) and YKL‐40 (r = 0.42) and IL‐6 correlated with YKL‐40 (r = 0.46)." (PMID 36440611, 2023). "A great number of studies reported that hematological parameters which can capture inflammatory conditions, such as neutrophils, lymphocytes, platelets, and CRP, are related to prognosis in cancer patients." (PMID 35702873, 2023). "Although high CRP levels have been linked to poor clinical outcomes in various types of cancers with ICI treatment, little is known about the direct effects of CRP on adaptive immunity in cancer." (PMID 38104105, 2023). "Nonetheless, CRP is widely used as a clinical biomarker of inflammation, is a predictor of CVD risk, and is associated with increased risk of all-cause and cancer mortality." (PMID 37347305, 2023). "CRP is a well-known prognostic factor for other cancers and for survival in surgically resected pancreatic G1-G3 NEN." (PMID 37872405, 2023). "Research has found that CRP produces inflammatory cytokines and chemokines that lead to cancer progression." (PMID 36831069, 2023). "Serum IL-6 and C-reactive protein (CRP) (cancer-promoting) are also elevated in SSc and correlate with clinical disease activity." (PMID 37681925, 2023). "According to reviews, increased neutrophil and monocyte counts, along with elevated levels of various inflammatory markers such as IL-6, IL-1β, and CRP, have been found to be correlated with fatigue in cancer survivors." (PMID 37507961, 2023).
cancer (continued). "IL-6, akin to C-reactive protein, is gaining prominence as a biomarker in monitoring inflammatory responses, particularly in cases of cancer, infections, or autoimmune disorders." (PMID 38162646, 2023). "Elevated acute-phase biomarkers, such as the C-reactive protein (CRP) and YKL-40 (also called chitinase-3-like-1 protein, CHI3L1), are associated with a poor prognosis for various types of cancer, including CRC." (PMID 37047727, 2023). "The ROC analysis of the non‐adjusted log2‐transformed variables showed that PSA (AUC = 0.72) and CRP (AUC = 0.69) had the highest AUC for the prediction of cancer." (PMID 36440611, 2023). "Since tumor-promoting inflammation is a typical feature of cancer, pioglitazone seems to be a promising agent due to its ability to decrease plasma C-reactive protein (CRP) levels by inhibiting interleukin 1 (IL1) expression." (PMID 36834531, 2023). "Cancer patients often have hyper-catabolic, hyper-inflammatory, and malnourished states, which can inhibit albumin synthesis via elevated C-reactive protein." (PMID 37438683, 2023). "We propose the Inflammatory Prognostic Score based on the blood levels of C-reactive protein and lactate dehydrogenase as well as the neutrophil-to-lymphocyte ratio to effectively monitor the effectiveness of comprehensive anti-cancer treatment." (PMID 36677048, 2023). "Similar findings were observed for incident cancer (baseline CRP, HR: 1.17; 95% CI: 1.09 to 1.26; ΔCRP, HR: 1.08; 95% CI: 1.01 to 1.15) and mortality (baseline CRP, HR: 1.29; 95% CI: 1.21 to 1.37; ΔCRP, HR: 1.10; 95% CI: 1.05 to 1.16)." (PMID 37019514, 2023). "CRP as an inflammation marker is a critical component of the complement system and can be found to be elevated in various cancers and autoimmune conditions." (PMID 38259852, 2023). "In fact, enhanced CRP is one component of the Glasgow prognostic score, which is a cumulative inflammation-based cancer prognostic marker composed of CRP elevation and a decrease in albumin concentration." (PMID 36441359, 2023). "In the current study, we report that initial as well as subsequent increases in CRP levels are associated with a greater risk of CVD, cancer, and death from any cause in the general population." (PMID 37019514, 2023). "C-reactive protein, lactate dehydrogenase, and neutrophil-to-lymphocyte ratio are important prognostic markers for cancer development." (PMID 36677048, 2023). "CRP, an acute‐phase protein, increases quickly in response to systemic inflammation, and relates to worse survival in various cancers." (PMID 35702873, 2023). "Various reports have regarded CRP levels as a strong indicator of poor prognosis in patients with cancer, including EC." (PMID 37346066, 2023). "Regarding sex differences, the CRP-based biomarkers of SIR showed stronger associations with all-cause, CVD and cancer mortality in males than in females, whereas the associations with respiratory disease mortality were comparable." (PMID 37340242, 2023). "Recently, Multiple cancer studies have demonstrated that the pre-transplant CRP/albumin ratio (CAR), as a composite index of statistical inflammation and nutritional condition, is an independent predictive predictor." (PMID 36875097, 2023). "Using a combination of C-reactive protein and albumin levels, the modified Glasgow Prognostic Score (mGPS) provides a prognostic score for patients who have cancer." (PMID 36923698, 2023). "Considering the existing literature, CRP appears to constitute a biomarker of growing importance for metastatic stages and survival in cancer patients." (PMID 37382699, 2023). "The Glasgow Prognostic Score includes both C-Reactive Protein (CRP) and albumin levels to predict survival in patients with cancer, and these biomarkers have been incorporated in other palliative prognostication tools as well." (PMID 37880704, 2023).
cancer (continued). "The mechanism underlying the observed usefulness of combining pre-CRT mGPS and post-CRT CRP levels can be attributed to cancer cachexia, cancer-derived inflammation, and CRT-induced inflammation." (PMID 37686634, 2023). "mGPS, defined by serum CRP and albumin levels, is a simple and objective parameter for assessing cancer cachexia, focusing on nutrition and systemic inflammation." (PMID 37686634, 2023). "Serum levels of IL-6, TNF-α, and other inflammatory and cancer-associated cytokines, as well as WBC, NEU, and CRP values, have a certain correlation with the development and progression of GLM; thus, they can reflect the disease to a certain extent." (PMID 37817809, 2023). "C‐reactive protein (CRP) >1.0 mg/dl was a poor prognostic factor for various cancers, but in this study, only number of BM and model formula were found to be associated with poor prognosis for CSS in multivariate analysis." (PMID 36305578, 2023). "Some studies have shown the usefulness of the combined immune status and nutritional assessment indices, such as the NLR/Alb, NLR/pre-Alb, and CRP/Alb ratios, in several cancers." (PMID 36983614, 2023). "The group of patients with a malignant tumor (n = 127) showed significantly higher values of CRP (p = 0.03) and the LEUK (p = 0.02) compared to other patients (n = 553)." (PMID 37079072, 2023). "It was reported that preoperative as well as postoperative serum CRP are both correlated with postoperative outcomes of patients with cancer." (PMID 37308992, 2023). "At the same time, as the most sensitive biomarker of inflammation, the increase of CRP level is one of the reasons for the poor prognosis of patients with malignant tumors." (PMID 37081512, 2023). "In conclusion, plasma CRP, IL‐6 and YKL‐40 alone or combined cannot be used to identify patients with cancer, but high levels were associated with poor prognosis." (PMID 36440611, 2023). "The CRP levels increased only in the control group, indicating inflammation, probably due to cancer progression and possible metastasis." (PMID 37083267, 2023). "In most studies, CRP levels were found to be highly elevated in patients with cancer and metastasis compared with the healthy control group or benign conditions." (PMID 37009523, 2023). "Systemic inflammation, diagnostically ascribed by measuring serum levels of the acute phase reactant C-reactive protein (CRP), has consistently been correlated with poor outcomes across cancer types." (PMID 37006231, 2023). "The potential of GINI is linked to the incorporation of two nutritional indices, namely albumin and CRP, which are also recognized as indicators of cancer cachexia." (PMID 37760482, 2023). "In several types of cancer, CRP elevation during the peri-treatment period has been reportedly associated with fatigue." (PMID 37373912, 2023). "The unadjusted univariate analyses showed increased risk of cancer with increasing plasma CRP, IL‐6, YKL‐40, CEA, CA 19‐9, CA‐125, PSA, age, former cancer diagnosis and PS ≥2." (PMID 36440611, 2023). "In accordance with earlier studies of patients with cancer, we found that high plasma concentrations of CRP, IL‐6 and YKL‐40 either alone or combined were associated with short OS in patients suspected of cancer." (PMID 36440611, 2023). "Patients diagnosed with cancer within 3 months had higher plasma CRP (p < 0.001), IL‐6 (p < 0.001), YKL‐40 (p < 0.001), CA 19‐9 (p < 0.001), CEA (p < 0.001), CA‐125 (p = 0.0075) and PSA (p < 0.001) than patients not diagnosed with cancer." (PMID 36440611, 2023). "First, GSVA analysis indicated that the CRP high subgroup was enriched for various cancer-promoting pathways, including Wnt/-catenin, TGF-, and JAK/STAT signaling, which overlapped with Cu ClusterB." (PMID 37007130, 2023).
cancer (continued). "In the current study, we examined associations of longitudinal changes in CRP with clinical correlates as well as with incident CVD, incident cancer, and all-cause mortality in 9253 individuals from two longitudinal community-based cohorts." (PMID 37019514, 2023). "Prospective studies suggest a heightened vulnerability to cancer among individuals with elevated serum CRP levels." (PMID 38201520, 2023). "Further studies with a larger number of patients and various cancer types are needed to validate the new CRP kinetics criteria as a useful biomarker in ICI treatment." (PMID 39516365, 2023). "Even after adjustment for potential confounders (age, gender, BMI, smoking, lesion locations, cancer histological type and stage, PT, APTT, triglycerides, HDL-C, WBC, platelets, and CRP), the association was significant." (PMID 34991557, 2022). "In this latter study one probable explanation for the low accuracy is the use of cancer diagnosis as a marker of inflammation instead of CRP, as recommended previously." (PMID 36483923, 2022). "CRP levels are increased in patients with several diseases such as cancer, HIV, or cardiovascular diseases and elevated CRP levels are related with higher mortality." (PMID 35493955, 2022). "We found that high NMPR was significantly associated with several unfavorable factors including longer tumor length, advanced T stage and high CRP level, supporting a potential association of NMPR with increased inflammation induced by cancer progression." (PMID 36557010, 2022). "The SIS combines albumin and LMR values and has been noted to be superior to other blood-borne markers like the NLR, modified Glasgow Prognostic Score, and lymphocyte C-reactive protein score for patients with cancer." (PMID 36338660, 2022). "The survival of patients with cancer was prospectively assessed in another study, demonstrating that high levels of tB12 and C-reactive protein (CRP) are two independent biomarkers for a worse prognosis." (PMID 35631199, 2022). "As an acute inflammatory response biomarker, serum CRP has been recognized as an indicator of progression for several malignant tumors." (PMID 35185894, 2022). "IL-6 represents the degree of inflammation in cancer tissue, and IL-6 elevation leads to increased CRP and decreased serum albumin." (PMID 36260237, 2022). "Glasgow prognostic score (GPS) is a score that includes the serum level of CRP and albumin reflecting the immunological and nutritional status of cancer patients." (PMID 35756636, 2022). "The risk of all-cause mortality (47.6% vs. 34.9%, p < 0.001), cardiovascular related mortality (10.5% vs. 7.2%, p < 0.001) and malignant neoplasms related mortality (10.1% vs. 8.2%, p = 0.049) increased with hs-CRP level elevation (p < 0.05)." (PMID 36338499, 2022). "The study of inflammation bio-markers, such as neutrophils, lymphocytes, CRP and platelets, has shown some correlation with poor oncological prognosis in several cancers (gynecological, digestive and thoracic)." (PMID 36428784, 2022). "In bivariate analysis, it was noted that groups with high NLR, dNLR, PLR, BLR, SII, ESR, CRP, and procalcitonin, and groups with low LMR, BAN score, and PNI groups had significantly higher association with advanced-stage cancer." (PMID 36614896, 2022). "•Women with elevated CRP of ≥5.5 mg/L had a 68% increase in overall and a two-fold increase in cancer-specific mortality." (PMID 34802721, 2022). "Serum concentrations of IL–6 and CRP are known to be positively correlated with each other, and recent evidence suggests that IL–6 also affects the rate of cancer progression." (PMID 34980029, 2022). "Multivariable-adjusted Cox proportional hazards model was conducted to evaluate the observed correlation of CRP with overall cancer and 21 site-specific cancer risks." (PMID 36117174, 2022).
cancer (continued). "After performing the non-parametric U Mann–Whitney test comparing the concentrations obtained in both groups, we observed that the levels of CCL2, CCL4, CEA, and CRP in the entire cancer group were significantly higher (in all cases p < 0.05)." (PMID 35407400, 2022). "We therefore considered the CRC stage and serum CRP level to be potential confounders for oxidative stress, and we adjusted for age, sex, smoking and drinking habits, cancer stage, and CRP levels when we performed the partial correlation analyses." (PMID 36076975, 2022). "Higher baseline inflammation, measured by fibrinogen and C-reactive protein (CRP) levels, has been show to increase cancer risk and mortality." (PMID 35979450, 2022). "Subsequently, CRP returns to the tumor microenvironment and promotes the autocrine growth of malignant tumors as an opsonin." (PMID 36096761, 2022). "The increase in CRP levels in patients with end-stage cancer is mainly related to tumor progression and inflammatory response." (PMID 36684183, 2022). "Patients with malignancies, chronic renal disease, bacterial infections, and body mass index (BMI) > 30 kg/m2 were excluded, as these conditions can increase CRP and/or ESR." (PMID 35888074, 2022). "Many inflammation-based scores such as the ratio of C-reactive protein to albumin are related to prognosis of several cancers, including HNC." (PMID 35954360, 2022). "IL-6 induces C-reactive protein production and affects cancer cell proliferation, invasion, metastasis, angiogenesis, and resistance to treatment via the JAK/STAT3 pathway." (PMID 36294421, 2022). "A meta‐analysis of cancer‐focused research found that combined resistance and endurance exercise training lead to reductions in CRP in cancer survivors." (PMID 36251564, 2022). "Specificity was 45.9% (95% CI 44.7–47.1), compared to 90.0% for FIT alone (in the subset with serum ferritin and CRP), leading to one cancer in every 57 positive tests compared to one in 12 in the FIT-only approach." (PMID 35287679, 2022). "Cancer-related systemic inflammation has been regarded as a pivotal determinant of disease progression and survival in most cancers; CRP is among these inflammatory markers." (PMID 35847918, 2022). "Patients with cancer often have systemic inflammation, and a combination of serum CRP and albumin level is used as a method for evaluating inflammatory response and nutritional status." (PMID 35204642, 2022). "Combined with this study, primary prophylactic anticoagulant therapy is recommended for advanced cancer patients with high risk factors (increased DD, FDP, CRP), such as low molecular weight heparin." (PMID 36439504, 2022). "Serum levels of inflammatory markers like CRP, IL-6 and TNF are associated with the incidence of several cancers and mortality in cohorts and meta-analyses in the general population, with a modest effect size." (PMID 35406394, 2022). "The mGPS was designed to predict survival in cancer patients using only C-reactive protein and albumin." (PMID 35215419, 2022). "TNF-α, C-reactive protein (CRP), and serum soluble interleukin-2 receptor (sIL2r) have also been associated with MDD in patients with cancer, directly modulating the HPA axis." (PMID 36185233, 2022). "Noteworthy, a significantly (P<0.001) higher CRP level was observed in patients with malignant tumors compared to patients with benign masses." (PMID 36532648, 2022). "As a clinically convenient technique, C-reactive protein has also been widely reported as a biomarker for the estimation of the association between SIRS and the long-term prognosis of cancer." (PMID 35203589, 2022). "Markers of the inflammatory response, including LMR, SLR, lymphocytes, NLR, and CRP, play important roles in the progression of many cancers." (PMID 36184588, 2022). "Of note, higher levels of inflammatory (IL-6, hs-CRP) and coagulation (D-dimer) markers are associated with an increased risk of cardiovascular disease (CVD), cancer, and all-cause mortality." (PMID 35359950, 2022).